TNF (tumor necrosis factor)
Diseases named in the same sentence as TNF in open-access papers (continued):
Sharing a sentence is not in itself a finding about the gene and the disease.
ischemic stroke (continued). "Tumor necrosis factor α (TNFα) is a proinflammatory cytokine that is synthesized in brain within 1 hour of an acute experimental ischemic stroke." (PMID 23840214, 2013). "Another meta-analysis results of 14 studies demonstrated that ischemic stroke patients have higher serum TNF-α level than the control subjects (standardized mean difference (SMD) = 2.33, 95% CI = 1.85 to 2.81)." (PMID 23050663, 2012). "The present systematic study examined the polymorphism of TNF-α gene promoter, circulating TNF-α levels, and traditional cardiovascular risk factor for ischemic stroke in the Chinese Han population." (PMID 23050663, 2012). "The present study found elevated IL-1β, IL-6 and TNF-α level in CSF at the sixth hour from ischemic stroke onset." (PMID 21450100, 2011). "Local expression of proinflammatory cytokines, particularly IFNγ and TNF, has been shown, in animal models, to worsen damage as incurred, for example, during ischemic strokes." (PMID 21941411, 2011). "IL-1β expression, like TNF-α, seems to promote infarction progression in animal models of ischemic stroke." (PMID 22082476, 2011). "In contrast, mice lacking both TNF receptors show increased infarct volume after ischemic stroke, and administration of TNF-α 48 hours prior to induction of MCAo results in a neuroprotective effect." (PMID 21040547, 2010). "The expression of adhesion molecules in the astrocytes by TNF-α is closely related to ischemic stroke development in the acute setting." (PMID 20700422, 2010). "Taken together, the results show that IL-1β and TNF-α are produced by largely segregated populations of microglia and macrophages after ischemic stroke in mice." (PMID 18947400, 2008). "In comparison, there is evidence that TNF-α has both neurotoxic and neuroprotective roles after ischemic stroke in rats and in mice." (PMID 18947400, 2008). "The objective of the present study was to provide additional insight into the cell types and cell subpopulations that produce IL-1β and TNF-α within the first 24 hours following ischemic stroke in mice." (PMID 18947400, 2008). "TNF-α exerts a dual effect on brain inflammation following the initial stages of ischemia, acting as an inflammatory promoter in the early phases and as an immunosuppressive agent in the chronic phase of ischemic stroke." (PMID 40364646, 2026). "In a rat ischemic stroke model, it inhibited the stimulation of microglia and astrocytes and decreased the expression of TNF-α, IL-1β, ıntercellular adhesion molecule (ICAM)-1, vascular cell adhesion molecule (VCAM)-1, inducible NO synthase (iNOS), and aquaporin-427." (PMID 40498951, 2025). "However, perampanel treatment significantly inhibited ischemic stroke-induced elevation of TNF-α, nNOS, and iNOS." (PMID 41148843, 2025). "To investigate whether GJC-CDs are involved in the inflammatory response in ischemic stroke, we examined the levels of TNF-α, IL-1β, IL-6, and IL-10 in the serum of each group of mice." (PMID 40573265, 2025). "Enhanced knowledge of the roles played by IL-6 and TNF-alpha may lead to novel therapeutic strategies that can optimize recovery and improve the overall quality of life for individuals affected by ischemic stroke." (PMID 39859987, 2025). "In addition to major cytokines like IL-1β, IL-6, TNF-α, and IL-10, several other inflammatory mediators play significant roles in ischemic stroke." (PMID 40869247, 2025). "This process amplifies the neuroinflammatory cascade and exacerbates secondary brain damage.This temporal disparity in cellular sources partially influences the functional shift of TNF-α from pro-inflammatory effects to potential protective roles in ischemic stroke." (PMID 41451205, 2025). "Itgam, as one of the potential core therapeutic targets in patients with ischemic stroke, may play a role by regulating the secretion of key inflammatory factors, IL-1β, IL-6 and TNF-α, and influencing neuronal apoptosis." (PMID 41181154, 2025).
ischemic stroke (continued). "Astrocytes influence synaptic damage or recovery at different stages of ischemic stroke through numerous proposed pathways such as glutamate clearance or secretion of factors such as TNF-α or thrombospondin, which are involved in synapse formation and function." (PMID 39103660, 2025). "Acupuncture may help reduce inflammation in ischemic stroke by lowering proinflammatory cytokines like IL-1β, IL-6, and TNF-α in the brain and blood." (PMID 40520194, 2025). "A study treating ischemic stroke with a monoclonal antibody targeting TNF- α found that the antibody favorably modulates microglial M1 / M2 polarization, rebalances Th 17 / Treg, cell dynamics, and suppresses Caspase-8-mediated GSDMD cleavage to prevent microglial pyroptosis." (PMID 40786625, 2025). "In the setting of an ischemic stroke, vitamin D may mitigate neuroinflammation by downregulating pro-inflammatory mediators such as interleukin 6 (IL-6) and tumor necrosis factor alpha (TNF-α), potentially limiting secondary neuronal damage." (PMID 40142657, 2025). "Considering the pivotal role of microglia in neuroinflammation following ischemic stroke through the production of pro-inflammatory factors such as IL-1β, TNF-α, and IL-6,28 we assessed the expression of these pro-inflammatory factors in both MCAO and OGD/R models." (PMID 40831534, 2025). "By dampening TNF-α generation and release, IMiDs can potentially reduce the overall inflammatory cascade, thereby minimizing the extent of neuronal damage and improving outcomes in ischemic stroke." (PMID 40095189, 2025). "This suggests that the protective effect of intranasal BDNF in ischemic stroke might be partially due to the downregulation of TNF-α and the upregulation of IL-10." (PMID 40895108, 2025). "Our study aims to synthesize current knowledge on the roles of IL-6 and TNF-alpha in ischemic stroke, explore their potential as biomarkers for disease progression and prognosis, and correlate the degree of disability in ischemic stroke patients with plasma concentrations of these two biomarkers." (PMID 39859987, 2025). "TNF-α is a pivotal early mediator of inflammation following ischemic stroke." (PMID 40869247, 2025). "Furthermore, ischemic stroke also stimulate glial cells and macrophages, giving rise to the secretion of many inflammatory cytokines such as IL-6 and TNF-α, leading to inflammation and neuronal cell death." (PMID 39683536, 2024). "Indeed, TNF-α is released in the brain during ischemic stroke and has been shown to mediate cell death." (PMID 38732147, 2024). "Likewise, increased plasma levels of IL-1β, IL-6, and TNF-α have been reported in ischemic stroke patients." (PMID 36536168, 2024). "Additionally, AMA rats had significantly higher levels of TNF-alpha and total oxidant capacity after experiencing an ischemic stroke." (PMID 39309404, 2024). "Furthermore, microglia-derived TNF-α has been shown to be the major factor exacerbating BBB impairment after ischemic stroke." (PMID 39766497, 2024). "Therefore, therapeutic electrical stimulations modulated the decrease in inflammatory cytokines, including IL-1β and TNF-α, in the ischemic stroke mice model by activating the STAT1 and NF-kB signaling pathways." (PMID 39062789, 2024). "In ischemic stroke, local inflammation and thrombosis are accompanied by elevated levels of TNF-α." (PMID 39771032, 2024). "While only a limited number of studies have explored the pathophysiology of MICS in ischemic stroke, there is substantial evidence indicating that inflammatory cytokines, such as tumor necrosis factor, can contribute to tissue degradation and facilitate the loss of skeletal muscle." (PMID 39458457, 2024). "We found that PTS decreased HDAC3 expression and activity, increased Nrf1 acetylation in the cell nucleus and inhibited the interaction of Nrf1 with p65 and p65 accumulation, which reduced infarct volume and neuroinflammation (iNOS/Arg1, TNF-α and IL-1β levels) after ischaemic stroke." (PMID 39198723, 2024).
ischemic stroke (continued). "Because microglial polarization to the M2 type promotes brain repair and confers a beneficial effect after ischemic stroke, we investigated whether 2′-FL regulates IL-10 and TNF-α secretion using ELISA." (PMID 37372011, 2023). "Both in vivo and in vitro studies have demonstrated that factors relevant to ischemic stroke, including bradykinin, histamine, NO, tumor necrosis factor (TNF)-α, platelet-activating factor, and VEGF, can lead to increased NO-cGMP dependent paracellular permeability." (PMID 37840921, 2023). "In particular, TNF-α has been shown to correlate with poor clinical outcomes after ischemic stroke." (PMID 34853925, 2023). "In an ischemic stroke mouse model, pretreatment with TwX (20 mg/kg/day) for 14 days resulted in reduced infarct size and reduced expression of OS markers, tumor necrosis factor-α (TNF-α), and inflammation markers." (PMID 38068966, 2023). "Using transcriptomics, mouse astrocytes have been shown to adopt a neurotoxic ‘A1’ phenotype upon exposure to LPS activated microglia-derived IL-1⍺, TNF and C1q and alternately, they can adopt a neuroprotective ‘A2’ phenotype in ischemic stroke; both of which are acute pathological states." (PMID 38015828, 2023). "IL-6 and TNF-α are the major inflammatory factors released following ischemic stroke." (PMID 36755018, 2023). "However, previous studies have shown that following experimental and human ischemic stroke, the expression levels of TNF-α and its two identified receptors (TNFR1 and TNFR2) are elevated and can influence the progression of infarct." (PMID 36769472, 2023). "Immediately after ischemic stroke, immune cells in the central nervous system are excessively activated, leading to the release of several inflammatory factors, such as IL‐1β, IL‐6, and TNF‐α." (PMID 37062886, 2023). "In addition to being involved in neuroinflammatory responses after ischemic stroke, TNF-α entering the bloodstream helps trigger inflammatory cascades." (PMID 36211352, 2022). "The same frequency interval (1–20 Hz) may reduce the levels of pro-inflammatory cytokines, including IL-1b, IL-6, and TNF-α, in rats following ischemic stroke." (PMID 35055089, 2022). "Studies have suggested that the release of astroglial and microglial TNFα may be neuroprotective in a model of ischemic stroke." (PMID 36009104, 2022). "Our laboratory has also shown smoking exposure (both tobacco smoke and electronic nicotine vaping) is associated with aggravated brain edema as well as reduced antioxidative molecule NRF2 and increased proinflammatory cytokine TNFα in mouse brain under normoxic and/or ischemic stroke conditions." (PMID 35672716, 2022). "In addition, other top immune genes are IL6 and TNF, which are also important immunoinflammatory molecules that participated in ischemic stroke." (PMID 35419038, 2022). "Moreover, the KEGG Mapper results further showed that IL-1β, TNF-α, IL-6, and IL-4 are core potential targets involved in Epimedium-mediated neuroinflammation following ischemic stroke." (PMID 36338345, 2022). "Following an ischemic stroke, TNF levels rise in cerebrospinal fluid (CSF) and blood." (PMID 35432523, 2022). "In an ischemic stroke setting, TNF-α is involved in inflammatory and prothrombotic events." (PMID 36361836, 2022). "In addition, ELISA showed that levels of pro‐inflammatory factors (IL‐1β, IL‐6, TNF‐α) were increased after ischemic stroke." (PMID 35695696, 2022). "The purpose of the research was to assess the concentration of pro-inflammatory cytokines IL-6 and TNF-α in the blood serum of patients with ischemic stroke (AIS) and to investigate their role as new markers in predicting functional prognosis after thrombolytic therapy." (PMID 36142524, 2022). "Studies have demonstrated that PPAR-γ activation could reduce pro-inflammatory cytokines such as TNF-α and promote white matter integrity after ischemic stroke." (PMID 35642056, 2022).
ischemic stroke (continued). "In addition, IL-16 promotes the production of inflammatory cytokines such as TNF-α, IL-1β, and IL-6, which has key effects in immune responses after ischemic stroke." (PMID 35173738, 2022). "For example, an article published by Brain Behavior and Immunity focuses on a natural product, pinocembrin, which has been shown to improve neuroinflammation and effectively reduce the expression of inflammatory factors such as IL-6,TNF-α in the brain tissue of patients with ischemic stroke." (PMID 36389810, 2022). "TNF-α may be one of the most widely studied cytokines in the inflammatory response after ischemic stroke." (PMID 36211352, 2022). "In this study, we analyzed the pathological effect of TNF-α in a mouse model of ischemic stroke." (PMID 35781632, 2022). "TNF is a versatile pro-inflammatory cytokine involved in all stages of ischemic stroke." (PMID 35388303, 2022). "Plasma TNF levels were comparable in controls and ischemic stroke patients (p = 0.50)." (PMID 33918875, 2021). "In addition, proinflammatory cytokines, including IL-1, IL-6, IL-17, and TNF-α, have been detected in the brain of ischemic stroke patients and the infarction area of animal models." (PMID 33777318, 2021). "Furthermore, in one case a sibling subsequently developed an ischemic stroke at age 21, after declining treatment with anti-TNF therapy." (PMID 35095905, 2021). "Similar to the result, we hypothesize that alterations of TNF-α, IL-1β, and IL-6 concentrations in CSF are more suitable to represent inflammatory response after ischemic stroke." (PMID 34257822, 2021). "Similarly, higher TNF-α expression levels were found to be consistent with higher microglial phagocytosis after ischemic stroke." (PMID 34956584, 2021). "TNF-α enhances the detrimental effects of IL-1β, and antagonism of IL-1β either through anti-IL-1β antibodies or administration of the IL-1Receptor antagonist (IL-1RA) has been shown to be neuroprotective and improves outcomes after ischemic stroke." (PMID 34572077, 2021). "Laminarin, a dectin-1 antagonist, reduced the number of IBA1-positive cells and the expression of tumor necrosis factor and induced nitric oxide synthase on the third day after ischemic stroke, which reduced the volume of cerebral infarction and improved nerve function." (PMID 34094602, 2021). "However, the exact role exerted by TNF and its two receptors in the context of ischemic stroke is still controversial." (PMID 33918875, 2021). "In line with our studies, serum TNF levels were unchanged in ischemic stroke patients." (PMID 32503645, 2020). "Previous study has revealed that TNF-α mediates endothelial necroptosis aggravating blood-brain barrier disruption after ischemic stroke, which might explain the reason why ambroxol relieves brain water content in the present work." (PMID 32309438, 2020). "In silica study showed that RQKL may regulate PI3K-Akt, estrogen, neurotrophin, HIF-1, MAPK, Hippo, FoxO, TGF-beta, NOD-like receptor, apoptosis, NF-kappa B, Wnt, chemokine, TNF, Toll-like receptor signaling pathways against ischemic stroke." (PMID 32457601, 2020). "Treatment of ischemic stroke with a Dectin-1 antagonist or a Syk inhibitor significantly decreased microglial activation, the brain infarct volume, neurological impairment, and production of the proinflammatory cytokines TNF-α and iNOS after ischemic stroke." (PMID 31926564, 2020). "This suggests that TNF-α plays a crucial part in the pathogenesis of ischemic stroke." (PMID 32714405, 2020). "Moreover, recent studies reported that increased Tim-3 expression in peripheral blood mononuclear cells in ischemic stroke patients and in brain tissue of ischemia-reperfusion mice positively correlated with plasma IL-17 and TNF-α levels." (PMID 33168786, 2020). "The present study indicated that borneol may be a potential anti-inflammatory drug, particularly in respect to cytokine suppression, resulting from the decreased expression of TNF-α induced by ischemic stroke." (PMID 30863478, 2019).
ischemic stroke (continued). "The severity of CAS was found to be correlated with PTX3 and TNF-α levels, which in turn might reflect the degree of inflammation, and may give predictive information about long term outcome in patients with ischemic stroke." (PMID 31998222, 2019). "Ischaemic stroke induced massive production of TNF‐α, IL‐1β and IL‐6 in Iba‐1+ cells." (PMID 31087489, 2019). "In addition, EA treatment inhibits microglia-mediated neuroinflammation through inactivation of p38 MAPK and MyD88, accompanied by the decrease of IL-1β, IL-6, and TNF-α after ischemic stroke." (PMID 31866829, 2019). "In ischemic stroke, TNF plays an important role in infarct development." (PMID 31440125, 2019). "1–20 Hz EA treatment were inserted at 2–3 mm depth into Quchi and Zusanli, and may reduce the levels of pro-inflammatory cytokines, including IL-1β, IL-6, and TNF-α, in rats following ischemic stroke." (PMID 30618558, 2018). "In-vitro experiments revealed that the phagocytic capability of alveolar macrophages was reduced and the expression of TNF-α and IL-6 was increased in alveolar macrophages isolated from naïve rats only after exposure to serum from rats that had experienced ischemic stroke." (PMID 30290827, 2018). "Our observation that ischemic strokes are associated with a significant increase in DAD score and lung ultrastructural changes might be explained by higher levels of TNF-α and IL-6 in the plasma and lungs, and of TNF-α in BALF." (PMID 30290827, 2018). "Therefore, a long-term observational study is required to understand the role of TNF-α in ischemic stroke treated with paeonol." (PMID 28101118, 2016). "Meta-analysis results of 14 studies (671 cases and 534 control subjects) demonstrated that ischemic stroke patients have higher serum TNF-α level than the control subjects (SMD = 2.33, 95% CI 1.85 to 2.81), although significant heterogeneity was present (I2 =0.9, Pheterogeneity < 0.0001)." (PMID 23050663, 2012). "On cytokine level of brain local inflammation in ischemic stroke, we found that BDNF could decrease brain TNF-α in ischemic stroke." (PMID 21490702, 2010). "TNF-α is produced by microglial cells and infiltrating macrophages following ischemic stroke and may have neurotoxic and/or neuroprotective effects." (PMID 20700422, 2010). "We investigated whether IL-1β and TNF-α are synthesized by overlapping or segregated populations of cells after ischemic stroke in mice." (PMID 18947400, 2008). "Whereas IL-1β is primarily neurotoxic in ischemic stroke, TNF-α may have neurotoxic and/or neuroprotective effects." (PMID 18947400, 2008). "The relative physiological outcome of increased IL-1β and TNF-α signaling in ischemic stroke may depend on the kinetics and location of cytokine producing cells." (PMID 18947400, 2008). "Two pro-inflammatory cytokines, TNFα and IL1β, that are known to trigger disruption of paracellular barrier properties in primary brain endothelial cells in vitro and are upregulated after ischemic stroke, contribute to Rab7a activation in primary mouse brain endothelial cells (BECs)." (PMID 41024170, 2025). "Pathway enrichment analysis revealed that PA may exert its protective effects against ischemic stroke by primarily targeting the response to reactive oxygen species, metabolic processes related to reactive oxygen species, TNF signaling pathway, HIF-1 signaling pathway, and IL-17 signaling pathway." (PMID 38448479, 2024). "However, the effect of TNF-α in ischemic stroke is controversial." (PMID 37486903, 2023). "However, ablation of soluble TNF-α is neuroprotective in ischemic stroke." (PMID 37486903, 2023). "Regulation of IL-1 and TNF cytokine families could also help attenuate ischemic stroke injuries." (PMID 35794095, 2022).